IL4R (interleukin 4 receptor)
Diseases named in the same sentence as IL4R in open-access papers (continued):
Sharing a sentence is not in itself a finding about the gene and the disease.
asthma (continued). "Dupilumab, a monoclonal antibody targeting IL-4Rα, has shown promise in managing recalcitrant atopic dermatitis and asthma, but data in immunocompromised pediatric populations remain limited." (PMID 41357247, 2025). "It is a fully human mAb targeting the IL-4 receptor alpha (IL-4Rα) and IL-13 and has significantly advanced the treatment landscape for patients with moderate-to-severe asthma, particularly those with type 2 inflammation." (PMID 40564060, 2025). "Biologic therapies targeting the IL-4/IL-13 pathway, such as anti-IL-4Rα monoclonal antibodies (mAbs), have shown improvements in lung function and reductions in exacerbation rates for severe asthma." (PMID 40370530, 2025). "Our data suggest that the positive impact of anti-IL-4Rα therapies such as dupilumab on asthma exacerbations in terms of reduced exacerbation frequency and severity is due to inhibition of pro-inflammatory T2 immune." (PMID 40370530, 2025). "Dupilumab, an IL-4Rα antagonist, has demonstrated efficacy across multiple type 2 diseases, including asthma, atopic dermatitis, CRSwNP, and eosinophilic COPD." (PMID 41294800, 2025). "Dupilumab, an IL-4Rα antagonist, provided substantial benefit in asthma and atopic dermatitis, yet 30–40% of patients remained partial or non-responders." (PMID 41294800, 2025). "Dupilumab, an anti–IL-4Rα monoclonal antibody, blocks IL-4R–mediated signaling and was approved for atopic dermatitis in 2017 and for asthma in 2018 by the Food and Drug Administration." (PMID 40561016, 2025). "Increased IL-4Rα expression in airway epithelium has been reported in asthma, particularly atopic/allergic asthma." (PMID 40170850, 2025). "Despite being hypothetical, this can beachieved with biological combinations such as anti-IgE, anti-IL5/IL-5R, and anti-IL-4R.However, studies with these combination treatments are needed in this CRSwNP eosinophilicsevere asthma phenotype to achieve this." (PMID 40145823, 2025). "This systematic review shows that approximately half of patients with ATS/ERS-defined severe asthma worldwide meet eligibility criteria for at least 1 biologic therapy targeting IgE, IL-5/IL-5Rα, or IL-4Rα." (PMID 41488544, 2025). "IL-4 and RV infection induced a significant increase in thymic stromal lymphopoietin (TSLP) levels in BECs from asthma compared with healthy, which was normalized by IL-4Rα mAb." (PMID 40370530, 2025). "BAs such as anti-IgE, anti-IL5, and anti-IL-4/IL-13 monoclonal antibodies (mAb) were found to be effective in the CRSwNP treatment of patients with severe asthma, with the most significant reduction being observed in the anti-IL-4R-mAb-receiving group." (PMID 38541174, 2024). "Dupilumab, anti-IL-4R Ab, which suppresses the IL-4 and IL-13 signaling, is applicable for treating severe cases of asthma, chronic sinusitis with polyps, and atopic dermatitis." (PMID 39624446, 2024). "Of these, IL-6 is a target for a therapy that is in phase II clinical trials to treat severe asthma (clazakizumab), and IL-4R is a target for dupilumab, which has been tested in clinical trials for uncontrolled severe asthmatics." (PMID 39197446, 2024). "Together, despite differences across models, mouse models supported a focus on therapeutic targeting of the IL-4/IL-4Rα/IL-5/IL-13 pathways for asthma treatment." (PMID 40047886, 2024). "Nowadays, dupilumab, an antibody directed against the interleukin‐4 receptor subunit α (IL-4Rα), targeting other type 2 inflammatory diseases such as asthma and atopic dermatitis, is approved for the treatment of EoE." (PMID 39230674, 2024). "Dupilumab, a monoclonal antibody targeting the IL4Rα subunit, has shown efficacy in mitigating type 2 inflammatory diseases, including asthma and CRSwNP." (PMID 39171052, 2024). "As far as IL-4Rα contributes to both IL-4 and IL-13 signaling, it is considered to be a prospective target for anti-Th2 cytokine therapy in asthma." (PMID 39767651, 2024).
asthma (continued). "In fact, some articles suggest the upregulation of IL-4R or TSLPR in the immune cells of patients with asthma." (PMID 39624446, 2024). "Patients treated with anti-IL4Rα therapy tended to have the least severe disease; however, all subsequent analyses were adjusted for baseline for all asthma outcomes assessed." (PMID 38711495, 2024). "Benralizumab, dupilumab, and reslizumab are mAbs to IL-5R, IL-4R, and IL-5, respectively, the biologics currently approved worldwide for allergic diseases such as asthma and atopic dermatitis." (PMID 38419685, 2024). "Dupilumab, a human monoclonal antibody targeting the alpha subunit of the interleukin-4 receptor, effectively inhibits IL-4 and IL-13 signaling, which are crucial pathways in type 2 inflammatory diseases such as asthma." (PMID 39280557, 2024). "IL-4 and IL-4R are known to be key players in allergic airway inflammation and asthma development and progression." (PMID 39767651, 2024). "We identified genetically driven pathways regulating eosinophilia in asthma, with two genes (IL4R, TSLP) targeted by drugs currently available for eosinophilic asthma." (PMID 37186423, 2023). "Currently, three classes of monoclonal antibodies targeting type 2 inflammation pathways are available in Italy for the treatment of severe asthma: anti-IgE (Omalizumab), anti-IL-5/anti-IL-5Rα (Mepolizumab and Benralizumab), and anti-IL-4Rα (Dupilumab)." (PMID 37298514, 2023). "Compared with the 6-month pre-treatment period (before the first injection of dupilumab), the median number of asthma exacerbations dramatically decreased from 4.0 (2.0-5.0) to 0.0 (0.0-0.0) (p < 0.0001) after 6 months of anti-IL4R/IL-13R therapy." (PMID 37063895, 2023). "Anti-IL5, anti-IL4R and anti-IgE mAbs have been used to improve outcomes from patients suffering from T2-high asthma endotypes." (PMID 37334374, 2023). "Dupilumab, an anti-IL-4Rα monoclonal antibody, is expected to be effective in eosinophilic airway inflammatory diseases, such as refractory asthma and chronic rhinosinusitis (CRS)." (PMID 37076824, 2023). "Due to this connection, dupilumab, an anti-IL4Rα mAb approved for asthma treatment, and tezepelumab an anti-TSLP mAb also approved for asthma treatment are also being tested in COPD patients with eosinophilia via randomised clinical trials." (PMID 37334374, 2023). "Dupilumab, the first fully human anti-IL-4 receptor mAb, approved in 2018 for add-on maintenance treatment of severe asthma, blocks both IL-4 and IL-13 from binding to IL-4Rα." (PMID 38203353, 2023). "Dupilumab, a recombinant monoclonal antibody specific for the type-I (IL-4Rα/γC) and type-II receptor (IL-4Rα/IL-13Rα), was recently approved for the treatment of AD, nasal polyposis, and asthma." (PMID 36614093, 2022). "Corticosteroids and biological therapies (e.g., anti-IL-4Rα, anti-IL-5/5Rα, and anti-IgE antibodies) have been indicated for asthma treatment in the guidelines of the Global Initiative for Asthma (GINA)." (PMID 35572500, 2022). "ALOX15, encoding 15 lipoxygenase 1 (15LO1), is one of the strongly and consistently expressed IL-4Rα–inducible transcripts by mucosal epithelial cells in T2-high asthma and CRSwNP." (PMID 34981786, 2022). "On the basis of the recommendations reported in step 5 of GINA (Global Initiative for Asthma) guidelines, currently available biological therapies for severe asthma include anti-IgE, anti-IL-5, anti-IL-5R and anti-IL-4R add-on treatments." (PMID 35625801, 2022). "IL-4R gene has been previously demonstrated as a potential asthma-related gene, located on chromosome 16p12.1." (PMID 36910341, 2022). "Antagonising the IL-4 receptor α subunit (IL-4Rα) interferes with the downstream IL-4/IL-13 signalling, which is central to the pathogenesis of asthma." (PMID 36140430, 2022).
asthma (continued). "A humanized monoclonal IgG4 antibody called dupilumab binds to the alpha subunit of the interleukin-4 receptor (IL-4Rα) and inhibits the signaling of IL-4 and interleukin-13 (IL-13), which has been successfully applied for atopic dermatitis and asthma." (PMID 35222408, 2022). "Dupilumab, an anti-IL4Rα, was approved in Europe in 2017 for atopic dermatitis and in 2019 for T2 asthma, while the anti-IL-5Rα benralizumab was approved for eosinophilic asthma in 2018." (PMID 35203504, 2022). "In patients with moderate-to-severe asthma, the treatment with dupilumab, an anti-IL-4Rα antibody, efficiently reduces severe exacerbation and improves lung functions, suggesting the involvement of IL-4 and/or IL-13 in the pathogenesis of asthma." (PMID 35693800, 2022). "IL-13 plays a key role in T2 asthma and blocking its receptor IL-4Rα with the antibody dupilumab is effective in controlling severe T2 asthma and preventing exacerbations." (PMID 35608088, 2022). "Dupilumab, the last approved mAb for the treatment of asthma, acts against the α chain of IL-4 receptor (IL-4R) that is common to both IL-4R and IL-13R." (PMID 34572466, 2021). "Signaling via IL4Rα is known to stimulate the production of the chemokine eotaxin by multiple lung cell types in patients with asthma." (PMID 33974563, 2021). "We performed a retrospective analysis of patients with severe asthma and comorbid CRSwNP who were treated with anti‐IgE, anti‐IL‐5/R or anti‐IL‐4R." (PMID 34331521, 2021). "The essential roles of IL-4 and IL-13 in the pathogenesis of allergic diseases, such as AD and asthma, were proven clinically by the efficacy of dupilumab, a monoclonal antibody for IL-4Rα." (PMID 34691223, 2021). "Murine asthma models have demonstrated a significant reduction in airway goblet cell metaplasia and eosinophilia following IL-4Rα mAb blockade." (PMID 33653328, 2021). "We conclude that IL-4Rα mAb blockade reduces excessive viral burden associated with HDM-sensitization and the concentration of pro-inflammatory markers associated with asthma exacerbation." (PMID 33653328, 2021). "Treatment by all antibodies showed effectiveness in reducing symptoms of CRSwNP in patients with severe asthma, with the largest reduction observed in anti‐IL‐4R‐treated patients." (PMID 34331521, 2021). "Targeting TL1A is therefore, more beneficial than targeting IL13/IL4Rα signaling in asthma and muco-secretory disorders." (PMID 34305924, 2021). "Whereas IL-13 has been a therapeutic target for asthma with ongoing clinical trials, dupilumab, anti-IL-4Rα which inhibits both IL-4 and IL-13 signalling, has been a front-runner treatment showing efficacy in severe asthma patients." (PMID 34127548, 2021). "Our findings indicate that prophylactic treatment with IL-4Rα mAb not only reduced asthma phenotypes such as airway goblet cell metaplasia and eosinophilia, but also improved disease severity by reducing weight loss and viral load." (PMID 33653328, 2021). "Currently available biologic therapies, including anti-IgE, anti-IL-5, anti-IL-5R⍺ and anti-IL-4R⍺, reduce asthma exacerbation rates in patients with Th2-high asthma." (PMID 33926084, 2021). "Alternative to anti-IL13 antibodies, IL4Rα antagonists (dupilumab) have been recently FDA approved as add-on-maintenance therapy to treat moderate-to-severe asthma." (PMID 34305924, 2021). "While the blockade of IL-4Rα has proven to be effective in reducing asthma severity, its clinical potential in ameliorating exacerbations of highly virulent influenza A infections has yet to be investigated." (PMID 33653328, 2021). "Due to its ability to relay signals for both IL-4 and IL-13, the blockade of IL-4Rα signalling has been of interest for alleviating asthma symptoms and severity." (PMID 33653328, 2021). "Similar lessons to focus on the phenotype-specific subjects were learned from the development of other Th-2-targeted asthma therapy, such as anti-IL-4R (Dupilumab) monoclonal antibody (mAb)." (PMID 35387016, 2021).
asthma (continued). "As the common receptor for both IL-4 and IL-13 signaling, blockade of IL-4 receptor alpha (IL-4Rα) has been touted as a method of alleviating asthma symptoms and severity." (PMID 33653328, 2021). "For example, we provide supporting evidence for a role of IL4R in asthma, IL2RA in thyroid dysfunction, and IL12B in psoriasis, as well as many cellular phenotypes, such as Transferrin receptor protein 1 (encoded by TFRC) in mean corpuscular hemoglobin." (PMID 32628676, 2020). "Anyway, the feasibility of intranasal treatment in ovalbumin-sensitized mice model for asthma has been proved with PEGylated dextran coated supermagnetic iron oxide nanoparticles (SPION) conjugated with anti-IL4Rα blocking antibodies." (PMID 32974295, 2020). "Dupilumab is profoundly involved in the amelioration of asthma by specifically binding to IL-4Rα shared by the IL-4 and IL-13 receptor complexes, inhibiting their signaling." (PMID 32019141, 2020). "Using GeneAtlas data, our analysis finds 5 proteins—all interleukin receptors—whose levels causally contribute to asthma disease risk: IL1RL1, IL1RL2, IL2RA, IL4R, and IL6R." (PMID 32628676, 2020). "Given the association between eosinophils and asthma, it is worth noting that IL1RL1, IL1RL2, IL2RA, and IL4R are all linked to ‘Eosinophil count’ and ‘Eosinophil percentage’ in GeneAtlas." (PMID 32628676, 2020). "In this context, recently, an anti-IL-4 receptor α subunit (IL-4Rα) antibody (dupilumab) was approved and is available for patients with asthma when standard treatment cannot provide adequate asthma control." (PMID 32019141, 2020). "Recent studies suggest that epithelial cell responses to IL-4/IL-13 increases the IL-4Rα-dependent smooth muscle contribution to airway hyper-responsiveness, supporting IL-4Rα-targeted therapy in asthma." (PMID 32509793, 2020). "This classification scheme differentiates Th2-high asthma, which is amenable to treatment with anti-IgE, anti-IL-5 or anti-IL-5Rα, and anti-IL-4Rα therapy, from Th2-low asthma." (PMID 32509793, 2020). "Our approach of temporal IL‐4Rα chain deletion supports a critical role in establishment and maintenance of disease and further highlights its therapeutic potential in many asthma disease endotypes." (PMID 31782803, 2020). "Current biologic treatments for severe asthma target a type 2-driven eosinophilic phenotype by blockade of IgE, IL-4Rα, IL-13, and, importantly, IL-5/IL-5Rα." (PMID 31415658, 2019). "Dupilumab, a monoclonal antibody blocking IL-4Rα, has been shown to be effective as a treatment of moderate-to-severe AD and moderate-to-severe asthma." (PMID 31708926, 2019). "Group 2 consists of the anti-IL-4Rα antibody, anti-IL-5 antibody, anti-IL-13 antibody, anti-IL-9 antibody, and anti-IL-17 antibody, which are the investigational drugs for asthma." (PMID 31284537, 2019). "Development of antagonistic antibody (Ab) against interleukin-4 receptor alpha (IL-4Rα) subunit of IL-4/IL-13 receptors is a promising therapeutic strategy for T helper 2 (TH2)-mediated allergic diseases such as asthma and atopic dermatitis." (PMID 31123339, 2019). "The anti-IL-4Rα antibody is directed against IL-4Rα and blocks the IL-4 and IL-13 pathways; this asthma treatment is under development." (PMID 31284537, 2019). "Dupilumab that blocks IL4Rα, a subunit of both the IL-4 and IL-13 receptors, interferes with the action of both these cytokines and to date has had success in treating asthma and atopic dermatitis." (PMID 29910811, 2018). "Corren and colleagues have tested the monoclonal IgG2 antibody AMG 317 from Amgen (Thousand Oaks, CA, USA) binding to IL-4Rα in a phase-II clinical trial in patients with moderate to severe asthma." (PMID 30500834, 2018). "Dupilumab, a monoclonal antibody against IL-4Rα developed and tested in clinical trials, has shown efficacy in atopic dermatitis, and asthma treatment." (PMID 28927416, 2017).
asthma (continued). "Phase III studies are underway which should provide more definitive information regarding the efficacy of blocking the IL-4Rα in asthma." (PMID 28721208, 2017). "IL-4/IL-4R antagonists have also been evaluated in clinical trials, but improvements in asthma symptoms were limited or inconsistent across studies." (PMID 26922672, 2016). "Underscoring the importance of this pathway are monoclonal antibodies against IL-13 and IL-4Rα that have shown considerable promise in early phase asthma clinical trials." (PMID 26605551, 2015). "The differentiation of Th2 cells plays an important role in asthma and Th2 cytokines, especially IL-4 and IL-13 which both can bind to the IL-4 receptor-alpha chain (IL-4Rα) and exacerbate disease." (PMID 24475277, 2014). "For example, DNA-M at the IL4R locus interacts with a local SNP to increase the RR of asthma much more dramatically than does either genotype or methylation alone." (PMID 25250096, 2014). "There is evidence that interleukin-4 (IL-4) and its receptor (IL-4R) are involved in the pathogenesis of asthma." (PMID 23286427, 2013). "We found that variants at MS4A2, IL4R and ADAM33 genes demonstrated varying association effects with the age at diagnosis of asthma, with 10 SNPs showing study-wise significance after the multiple comparison adjustment." (PMID 24039878, 2013). "Our results support the important role of MS4A2, IL4R and ADAM33 genes in asthma and/or atopy susceptibility." (PMID 24039878, 2013). "These cytokines are in the same inflammatory pathway as the IL4R gene and are all involved in the pathogenesis of allergy (e.g. asthma and rhinitis)." (PMID 23049769, 2012). "Treatment of mice with anti-IL-4, anti-IL-4Rα antibodies, or soluble IL-4Rα, inhibits the development of asthma." (PMID 22292924, 2012). "A three-way gene-gene interaction was elucidated between the gene coding glutathione S-transferase P (GSTP1), the gene coding interleukin-4 receptor alpha chain (IL4Ra) and the gene coding insulin induced gene 2 (INSIG2) on the risk of lifetime asthma." (PMID 22355322, 2012). "Several studies have shown the importance of these signaling molecules in asthma, but the roles of IL-4Rα and STAT6 in modulating specific features of airway inflammation were unclear." (PMID 22014099, 2011). "CD4+ T lymphocytes are important in the events leading to AHR in animal asthma models, via an IL-4R, STAT6 mechanism." (PMID 23283176, 2011). "Dupilumab, a biologic agent used in severe asthma, blocks IL-4 receptor alpha (IL-4Rα) and may offer therapeutic benefits in virus-induced asthma exacerbations." (PMID 41576028, 2026). "Dupilumab, a monoclonal antibody targeting IL-4 and IL-13 signaling via IL-4Rα inhibition, has emerged as an effective treatment for CRSwNP and asthma, offering significant reductions in nasal polyp burden, improvements in quality of life, and better asthma control." (PMID 41488423, 2026). "Dupilumab (anti-IL-4Rα) effectively controls severe asthma and CRSwNP and may improve upper and lower airway manifestations in EGPA; however, vigilance for vasculitic flares is advised in ANCA-positive subsets." (PMID 41303621, 2025). "Although genetics and other factors may contribute to increased IL-4Rα in asthma, investigating the role of IP is critical for enhancing our understanding of this important mechanism." (PMID 40170850, 2025). "Indeed, severe asthma patients treated with the anti‐IL4Rα antagonist dupilumab showed reduced numbers of circulating ILC2s, which contained lower levels of type 2 cytokine mRNA." (PMID 40016948, 2025). "Dupilumab is an IL-4Rα antibody approved for treatment of severe asthma." (PMID 40810090, 2025). "In airway-predominant disease (asthma ± CRSwNP), IL-4Rα blockade (dupilumab) may improve airway control, though caution is warranted in ANCA-positive phenotypes due to reported vasculitic flares." (PMID 41303621, 2025).